UBAP1L (ubiquitin associated protein 1 like)
Synonyms: UBAP-1L; RDZH
Tractability: No criterion of Open Targets' tractability assessment is met for any kind of drug.
Gene: Protein-coding gene on chromosome 15 (65,092,760 to 65,115,200, reverse strand). Ensembl gene ENSG00000246922.
Subcellular location (Human Protein Atlas): Nuclear bodies
Gene Ontology:
Molecular function: ubiquitin binding
Biological process: ubiquitin-dependent protein catabolic process via the multivesicular body sorting pathway
Cellular component: ESCRT I complex
Genetic constraint (gnomAD): Loss-of-function variants: 30 observed, 26.26 expected, observed/expected ratio (o/e) 1.14, 90% interval 0.85 to 1.55. The upper end of that interval is the gene's LOEUF score, 1.55, which puts it in group 6 of 6, group 1 being the genes least tolerant of losing a copy. Missense variants: 484 observed, 435.78 expected, observed/expected ratio (o/e) 1.11, 90% interval 1.03 to 1.2. Synonymous variants: 227 observed, 193.09 expected, observed/expected ratio (o/e) 1.18, 90% interval 1.05 to 1.31.
Homologues: Orthologues: chimpanzee UBAP1L (99% identical), dog UBAP1L (79% identical), rabbit UBAP1L (77% identical), pig UBAP1L (76% identical), rat Ubap1l (73% identical), mouse Ubap1l (69% identical), guinea pig UBAP1L (60% identical), tropical clawed frog ubap1l (41% identical), zebrafish ubap1la (34% identical), Drosophila melanogaster CG10435 (17% identical). Paralogues in human: UBAP1 (28% identical).
Diseases named in the same sentence as UBAP1L in open-access papers:
UBAP1L is named in the same sentence as 1 disease in open-access papers, as found by Europe PMC text mining. Sharing a sentence is not in itself a finding about the gene and the disease. The quoted sentences say what the papers report.
autosomal recessive rod-cone dystrophy (1 paper, 2025). "In autosomal recessive rod-cone dystrophy, ROs facilitated the validation of in silico predictions regarding an UBAP1L intronic variant." (PMID 39422807, 2025).